ALB (albumin)
Diseases named in the same sentence as ALB in open-access papers (continued):
Sharing a sentence is not in itself a finding about the gene and the disease.
aspiration pneumonia (14 papers, 2015 to 2025). "Serum albumin levels are also associated with mortality in aspiration pneumonia patients." (PMID 35748095, 2022). "Among the various factors associated with aspiration pneumonia, tracheostomy status, aspiration in VFSS, cough frequency, albumin levels, and cognitive function were identified as the key predictors." (PMID 41346384, 2025). "The GNRI consists of simple objective measurements, BMI and serum albumin, which can be easily obtained on admission in patients with aspiration pneumonia." (PMID 35789107, 2022). "GNRI consists of simple objective measurements such as BMI and serum albumin levels, which can be easily measured on admission for patients with aspiration pneumonia." (PMID 35789107, 2022). "Secondary outcomes included predictors of mortality, serum albumin levels, aspiration pneumonia and general complications." (PMID 25854831, 2015). "In addition, the BUN-to-serum albumin ratio is an important prognostic factor for mortality and severity in patients with aspiration pneumonia, hospital-acquired pneumonia, and community-acquired pneumonia." (PMID 38961438, 2024). "In withdrawn cases, reliable nutritional assessment parameters, such as albumin and SGA, were significantly lower compared to completed cases, and the most common reason for withdrawal was aspiration pneumonia (64.5%)." (PMID 31601040, 2019).
electrolyte disorders (14 papers, 2016 to 2025). "This disease is a self-limiting disease and can be gradually cured by rehydration, albumin infusion and correction of electrolyte disorders in moderate to severe cases." (PMID 37417637, 2023). "Before discharge, the patient’s BMI was 22.1 kg/m2, serum total protein was 66.8 g/L, albumin was 40.8 g/L, there was no electrolyte disorder, and the nutritional status was good." (PMID 40898474, 2025).
gestational diabetes mellitus (14 papers, 2018 to 2026). "Glycated hemoglobin A1c and glycated albumin levels in mothers of large-for-gestational-age newborns in correlation with gestational diabetes mellitus." (PMID 39600958, 2024). "For an example of the sandwich format, an LFA strategy tracked both glycated albumin and albumin concentrations in serum to record the glycemic status of patients with gestational diabetes mellitus (GDM), a glucose intolerance disorder in pregnant people." (PMID 37232930, 2023).
Hypernatremia (14 papers, 2013 to 2024). An abnormally increased sodium concentration in the blood. "Some anesthesiologists prefer using albumin to keep fluids intravascularly; diluting 25% albumin with an isotonic fluid avoids the acidosis and hypernatremia associated with the administration of large volumes of normal saline when using 5% albumin." (PMID 36178188, 2022). "Additionally, several laboratory parameters were identified, including platelet counts, hypernatremia, blood urea nitrogen, blood glucose levels, creatinine levels, and serum albumin." (PMID 38796444, 2024). "Moreover, findings from race A revealed a three percent increase in albumin and sodium concentration, results that suggest that the hypernatremia that occurred with endurance racing was due to a decreased water intake rather than being the result of sweating." (PMID 24167733, 2013). "Compared to the survivor group, patients in the non-survivor group demonstrated significantly elevated APACHE II and SOFA scores, as well as increased levels of PCT, Bun, hypernatremia, LUS and proportion of severe ARDS patients, while the albumin level was lower (all P < 0.05)." (PMID 39686985, 2024).
hypoparathyroidism (14 papers, 2013 to 2025). Hypoparathyroidism is an endocrine disorder in which the parathyroid glands in the neck do not produce enough parathyroid hormone (PTH). "A low serum albumin-adjusted calcium <2.0 mmol/L or <8 mg/dL in the presence of a low PTH <15 pg/mL is associated with a high risk of permanent hypoparathyroidism and requires appropriate supplementation with calcium and active vitamin D metabolites and follow-up." (PMID 30540559, 2019). "Published guidelines for the management of hypoparathyroidism during pregnancy recommend monitoring serum calcium concentrations every 3–4 weeks and maintaining the albumin-corrected calcium in the lower normal range." (PMID 37335755, 2023). "The diagnosis of hypoparathyroidism is made in the presence of low serum calcium (ionized or adjusted for albumin) and low or inappropriately normal PTH confirmed on two separate occasions." (PMID 30540559, 2019). "Close monitoring of circulating levels of calcium corrected for albumin, phosphate and magnesium is necessary to avoid complications of hypoparathyroidism in pregnancy." (PMID 30540559, 2019). "In group hypoparathyroidism when the effects of age, BMI and BUN, creatinine, eGFR, and albumin levels were adjusted in the partial correlation analysis, there was a significant relationship between cCa levels and PON levels (r=-0.315, p=0.04)." (PMID 33033457, 2020).
Osteopenia (14 papers, 2014 to 2025). Osteopenia is a term to define bone density that is not normal but also not as low as osteoporosis. "In men with normal bone density and those with osteopenia, significant differences were noted in age, height, weight, ALT, ALB, ALP, Cr, UA, BUN, TG, HDL-C, and Hb (P < .05)." (PMID 40859517, 2025). "In the current study, a marked albumin level reduction was observed in both normal BMD and osteopenia during chemotherapy." (PMID 28702147, 2017). "Based on the weighted analyses, participants with OP/osteopenia were more likely to have low serum uric acid levels, older, female, non-Hispanic White, BMI < 30, high HDL, low ALT, low AST, low albumin, low bilirubin, high alkaline phosphatase, high serum 25(OH)." (PMID 38898434, 2024).
primary biliary cholangitis (14 papers, 2009 to 2026). Primary biliary cholangitis (PBC) is a chronic and slowly progressive cholestatic liver disease of autoimmune etiology characterized by injury of the intrahepatic bile ducts that may eventually lead to liver failure. "However, it was reported that serum retinol levels are associated with biochemical parameters including albumin, total cholesterol, triglycerides, total bilirubin, and aspartate transaminase, and the hepatic histological findings of patients with primary biliary cholangitis." (PMID 30373117, 2018). "The Albumin-Bilirubin (ALBI) score and grade are widely used to stratify patients with primary biliary cholangitis (PBC) into different disease statuses and risk levels." (PMID 39568991, 2024). "Animals with biliary cirrhosis had a lower body weight, higher liver and spleen weights, lower levels of albumin and higher levels of other indicators of liver damage and fibrosis than the sham-operated rats (all P<0.05)." (PMID 25174394, 2014). "Human hepatocytes isolated from normal, normal resected and biliary cirrhosis showed significantly increased albumin synthesis after two days in culture." (PMID 21479238, 2011). "Stress induced BSA (bovine serum albumin) protein aggregation is effectively mitigated in vitro by TUDCA (tauroursodeoxycholic acid) than by PBA (4- phenylbutyric acid), chemical chaperones approved by FDA for the treatment of biliary cirrhosis and urea cycle disorders respectively." (PMID 28630443, 2017). "The lack of effect of albumin dialysis in significantly modifying the amino acid profile in primary biliary cirrhosis patients with bilirubin, prothrombin index and albumin levels within normal ranges may sustain this explanation." (PMID 19175915, 2009).
syphilis (14 papers, 2011 to 2025). A contagious bacterial infection caused by the spirochete Treponema pallidum. "Syphilis treatment improved liver function indicators, especially alanine aminotransferase, aspartate aminotransferase, bilirubin, and albumin." (PMID 34753447, 2021). "Less than a third of women were screened for haemoglobin estimation, albumin in urine and syphilis (10–28%), compared to an HIV test (50%)." (PMID 28722561, 2017). "Our study found that the mean albumin quotient was equal to or greater than 8.0 in neurosyphilis patients and non-syphilis neurological patients, which suggested that the blood brain barrier was damaged in these patients." (PMID 27376011, 2016). "CSF markers were negative for syphilis and borrelia, but the CSF/serum albumin ratio was slightly increased, indicating a blood brain barrier dysfunction although no cells were detected." (PMID 39849058, 2025).
Thromboembolism (14 papers, 2013 to 2025). The formation of a blood clot inside a blood vessel that subsequently travels through the blood stream from the site where it formed to another location in the body, generally leading to vascular occlusion at the distant site. "Previous studies have demonstrated that patients with albumin levels between 30 and 39.9 g/L have a 1.5-fold higher adjusted risk of thromboembolism compared to those with levels ≥ 40 g/L, with the risk increasing further at lower albumin levels." (PMID 39768925, 2024). "in which serum albumin was associated with increased 30-day mortality, major complications, wound infections, and thromboembolic disease." (PMID 36811703, 2023). "Because previous studies asserted that there was a modest association between low serum albumin and thromboembolism events in a larger cohort, which makes low serum albumin levels a clinical marker for thromboembolism, a higher leukocyte count has been significantly associated with thromboembolism." (PMID 36739380, 2023). "It is easy to implement into everyday clinical practice, as it includes four important parameters (age, IL-6, D-dimer, and serum albumin), reflecting the main pathophysiological mechanisms of the disease (inflammation, thromboembolism and cytokine storm)." (PMID 37627912, 2023). "Researchers also demonstrated a negative relationship between serum ALB levels and a risk of developing thromboembolism." (PMID 36514048, 2022). "Especially in patients with severe SARS-CoV-2-infection, albumin infusion may be essential to improve hemodynamics and to reduce the plasma level of the main marker of thromboembolism, namely, the D-dimer plasma level, as suggested by a recent report." (PMID 34281177, 2021).
alcoholic liver diseases (13 papers, 2012 to 2025). A disorder caused by damage to the liver parenchyma due to alcohol consumption. "Both alcohol misuse and alcoholic liver disease was significantly associated (p-value ≤ 0.05) with male gender, region of origin, number of life time sexual partners and serum albumin below 3.5 mg/dl after univariate and multivariate analysis." (PMID 24009799, 2013). "Our study suggests a link between alcohol misuse or alcoholic liver disease and male gender, region of origin, number of sexual partners, and serum albumin below 3.5mg/dl." (PMID 24009799, 2013). "Patients with mysteatosis had a significantly lower serum albumin (36 ± 11 g/L vs. 43 ± 5 g/L, p = 0.001) and suffered more often from alcoholic liver disease (38% vs. 13%, p = 0.005), while viral liver disease was observed less frequently (14% vs. 42%, p = 0.001)." (PMID 35158988, 2022). "To additionally explore the protective effect of AdoMet and Tyrosol against acute ethanol-induced cytotoxicity, we evaluated HepG2 cell release into the culture medium of some markers reported to be correlated to alcoholic liver diseases, such as transaminases, albumin, ferritin, and neutral lipids." (PMID 27128904, 2016). "In conclusion, we report a rare care of calciphylaxis in the setting of alcoholic liver disease that we believe is likely in the setting of low protein C and S levels along with low albumin levels, which does not allow for proper healing." (PMID 28589153, 2017).
bronchiectasis (13 papers, 2006 to 2025). Segmental, irreversible dilation of the bronchial tree resulting in the accumulation of secretions which leads to obstruction. "The main novel finding of the present study was the association of NTM infection in patients with bronchiectasis with lower values of several routine laboratory parameters, such as serum albumin and blood counts of lymphocytes and eosinophils." (PMID 39010067, 2024). "Statistically significant differences were observed in BMI, percentages of neutrophils, lymphocytes, and monocytes, absolute values of neutrophils, lymphocytes, and monocytes, aspartate aminotransferase level, and albumin level between the bronchiectasis and control groups (p < 0.05)." (PMID 41458288, 2025). "Basic information, imaging features, serum albumin levels, and infection indicators were collected from both groups of patients.Univariate and multivariate logistic regression analysis were performed to analyze the risk factors for NTM-PD in patients with bronchiectasis." (PMID 37986162, 2023). "The patients with COPD who died were older and presented with a longer duration of symptoms, a higher prevalence of bronchiectasis, a greater number of positive cultures of PPM, and a lower peripheral albumin concentration." (PMID 26077673, 2015). "A significant negative correlation was found between the HALPscore and albumin and the prevalence of bronchiectasis (number ofaffected lobes) (respectively p= 0.00, r= -0.33, p= 00, r=-0.025)." (PMID 38676590, 2024). "When subjects with bronchiectasis were excluded, a statistically significant relationship with TLCO could be demonstrated for LTB4 (rs = -0.432, p = 0.032, n = 29) but there was only a trend towards significance for albumin leak (rs = -0.241, p = 0.096, n = 29)." (PMID 17112387, 2006).
diabetic foot ulcer (13 papers, 2019 to 2026). "Study have pointed out that the joint assessment of ALB and NLR can predict the risk of diabetic foot ulcers." (PMID 40740647, 2025). "Compared with healthy foot patients, the levels of albumin, Hb, iron, and zinc were low in diabetic foot ulcer patients in our study." (PMID 38792906, 2024). "Using logistic regression analysis revealed only albumin and age to be independent predictors of diabetic foot ulcer mortality." (PMID 36588684, 2022). "In this regard, high RDW and low albumin may be a marker of poor general health and healing abilities of patients with diabetic foot ulcers." (PMID 41036136, 2025). "However, when compared to normal adult values, diabetic foot patients in our data exhibited significantly lower levels of hemoglobin, total protein, albumin, iron, zinc, copper, and HDL cholesterol." (PMID 38792906, 2024). "Low albumin has also been shown to contribute to poor wound healing in diabetic foot ulcers." (PMID 31864365, 2019). "Recent studies of patients with a diabetic foot ulcer showed that serum albumin levels were significantly lower than that in diabetic patients without a diabetic foot ulcer and that low albumin level was an independent predictor for delayed wound healing." (PMID 38792906, 2024).
dry eye (13 papers, 2010 to 2025). "The decrease of lactoferrin and lysozyme levels, as well as the increase of albumin are the most common electrophoretic changes in dry eye associated with CVS." (PMID 22567044, 2011). "In our previous study, 50 mg/mL albumin was applied as eyedrops for patients with severe dry eye caused by Sjogren's syndrome." (PMID 20360971, 2010). "Of these ALB, ANXA1 and ACTB have previously been seen upregulated in aqueous-deficient or Sjögren’s syndrome related dry eyes." (PMID 38368345, 2024). "The whole system has already been proven in other bioapplications such as dry-eye, Bovine Serum Albumin (BSA)/anti-Bovine Serum Albumin (aBSA), and anti-gestrinone antibodies." (PMID 30111765, 2018). "Such S/D treatment does not alter the plasma protein functionality or content, including albumin, which was shown to contribute to apoptosis suppression of ocular epithelium cells in a dry-eye model." (PMID 27100624, 2016). "Albumin has been used as eye drops for treating severe dry eye." (PMID 34201543, 2021). "The level of human serum albumin (HSA) may increase in tear secretions of patients suffering from dry eye syndrome and KC." (PMID 35011421, 2021). "Although chemical or mechanical stimulation could lead to an increased level of albumin originating from serum, the reflex tears can be used, especially in severe dry eye." (PMID 22567044, 2011). "One of the serum-derived candidates for the treatment of dry eye is serum albumin." (PMID 20360971, 2010). "In fact, albumin in tear film may serve as a double-edged sword, being detrimental to the ocular bioavailability of topically administered medications, but also beneficial for symptomatic relief of dry eye, corneal wound healing, and anti-oxidative and anti-inflammatory activities." (PMID 32047429, 2019). "Moreover, after 6 months of follow-up, the patient currently has no obvious symptoms of dry mouth and dry eyes, with normal albumin levels." (PMID 40292296, 2025).
eosinophilia (13 papers, 2011 to 2024). "Among patients with T2D, eosinophilia was associated with albumin excretion." (PMID 32961903, 2020). "Our data show increased airway eosinophilia, serum IgE, and albumin in the BAL fluid of mice up to 21 days after challenge with A. fumigatus, indicating a pathogenic role for A. fumigatus long-term persistence." (PMID 33597172, 2021). "Overall, mean creatinine and ESR levels were elevated, and levels of creatinine, LDH, albumin, SGPT, and ESR increased progressively with the severity of the eosinophilia." (PMID 39664150, 2024). "ETO metabolites were found in CSF months after implantation, 5/7 patients had CSF eosinophilia, 0/7 patients had peripheral eosinophilia, 2/7 patients had detectable serum IgE against albumin-ETO and experienced multiple shunt malfunctions without evidence of infection." (PMID 38500936, 2024).